MTOR (mechanistic target of rapamycin kinase)
Diseases named in the same sentence as MTOR in open-access papers (continued):
Sharing a sentence is not in itself a finding about the gene and the disease.
cancer (continued). "Additionally, IVM augmented the anti-cancer efficacy of cisplatin in ovarian cancer, both in vitro and in vivo models, by inhibiting the Akt/mTOR pathway, thus blocking downstream signaling required for cancer cell proliferation and survival." (PMID 41382246, 2025). "One downstream effect of mTOR signaling is to regulate cytokine production in cancer cells." (PMID 40385549, 2025). "Moreover, mTOR has been shown to impact tumor progression through dysregulated cellular signaling pathways in multiple cancers." (PMID 40535133, 2025). "In malignant tumors, aberrant activation of mTOR can lead to dysregulation of autophagy, which is closely linked to disruptions in tumor cell proliferation, invasion, migration, and interactions such as apoptosis and ferroptosis, ultimately accelerating GC progression." (PMID 40066330, 2025). "PI3K-AKT-mTOR signaling is dysregulated in human cancers, and mTOR inhibition induces autophagy." (PMID 40248706, 2025). "The PI3K/Akt/mTOR signaling pathway plays a dual role in both cancer cells and immune cells." (PMID 39744225, 2025). "In some cancer types, inhibiting the mTOR signaling pathway is thought to enhance drug sensitivity, suggesting that abnormal BCAA metabolism may promote resistance." (PMID 40438606, 2025). "Given that aberrant mTOR signaling is a well-established driver of tumor growth, EMT, metastasis, and resistance to cell death, targeting this pathway represents a compelling therapeutic strategy for preventing the progression of FA− deficient cancers." (PMID 40805278, 2025). "Additionally, the oncogenic activity of GOLPH3 has been linked with enhanced signaling downstream of mechanistic target of rapamycin (mTOR) in several cancer types." (PMID 40136688, 2025). "AKT2, a key player in the PI3K/AKT/mTOR signaling pathway, is frequently dysregulated in cancers, promoting tumor growth and therapeutic resistance The strong binding of complex 9 to AKT2 suggests its potential to disrupt this pathway, thereby inhibiting tumor proliferation." (PMID 40575462, 2025). "The mTOR signaling pathway is a definitive pathway in oncogenesis, critically involved in growth, metabolism, cell division, invasion, and malignant progression of human cancers." (PMID 39786317, 2025). "Moreover, this review highlights the role of the PI3K/AKT/mTOR axis in carcinogenesis, with significant emphasis on cancer growth, metastasis, therapy resistance, and immune interactions." (PMID 40740483, 2025). "However, dysregulation of the mTOR pathway is commonly observed in many cancers, where hyperactivation of mTOR drives uncontrolled cellular proliferation, enhances metabolic activity, and reduces autophagy, thereby contributing to tumorigenesis." (PMID 39940361, 2025). "As a result, PI3K/AKT/mTOR-targeted therapies are being promoted for many types of cancer." (PMID 40725184, 2025). "In addition, B-NGF activates the PI3K/AKT/mTOR signalling pathway mainly through TrkA receptors, further promoting cancer cell proliferation and immune escape." (PMID 40892159, 2025). "Given its crucial cellular roles, it is not surprising that mTOR has also been associated with ageing and human diseases including metabolic disorders, neurodegeneration and cancer." (PMID 40426219, 2025). "mTOR signaling plays a pivotal role in the development and progression of cancer." (PMID 40804480, 2025). "PD-L1 depletion can lower the rate of glycolysis by suppressing the expression of glycolytic enzymes and mTOR activity, indicating that PD-L1 may be essential for the uptake of glucose in cancer cells." (PMID 39858015, 2025). "The Review also discusses the implications of these findings for understanding complex biological systems and diseases, particularly cancer, where mTOR’s regulation of transcript diversity could drive tumor heterogeneity and treatment resistance." (PMID 40804480, 2025).
cancer (continued). "With the increasing focus on PI3K/Akt/mTOR inhibitors in cancer therapy, further exploring LINC00261-mediated regulation in this pathway could provide novel treatment strategies." (PMID 40136629, 2025). "Cancer cells may develop resistance to mTOR inhibitors over time by adapting or engaging alternative signaling pathways." (PMID 40558273, 2025). "The development of inhibitors targeting mTOR or EGFR has notably advanced cancer therapy." (PMID 40259053, 2025). "The PI3K/Akt/mTOR pathway is a promising target for anti-cancer compounds." (PMID 40387965, 2025). "mTOR inhibitors not only suppress these oncogenic processes but also inhibit T-cell activation and proliferation by downregulating IL-2 production, making them effective as both immunosuppressive and anti-cancer agents." (PMID 40098014, 2025). "It is well-known that PI3K-Akt-mTOR signaling pathway is closely related to cancers." (PMID 40253526, 2025). "On the other hand, normal cell hypertrophy, especially in myofibers, involves the activation of signaling molecules such as Myc, hypoxia-inducible factor, and Pi3k–Akt–mTor, which regulate metabolic reprogramming in cancer by increasing glucose uptake in the presence of oxygen." (PMID 41410298, 2025). "Naringenin regulate the autophagy of cancer cells by targeting the mTOR signal." (PMID 39754228, 2025). "PI3K/AKT/mTOR is the most crucial pathway in cancer inhibition." (PMID 38584538, 2025). "The importance of the PI3K/AKT/mTOR signaling pathway is highlighted by the fact that PIK3CA (catalytic subunit alpha) and PTEN (phosphatase and tensin homolog) have been identified as two of the most frequently mutated genes in cancer." (PMID 40725184, 2025). "mTOR signalling remains a appealing target for cancer treatment, including in leukaemia." (PMID 40425534, 2025). "Among these cellular pathways, mTOR and hypoxic signaling are interrelated in cancer cells." (PMID 41419193, 2025). "Targeting MYC and mTOR pathways may offer a more effective therapeutic approach in certain cancer-type, as it addresses multiple drivers for cancer growth and drug resistance." (PMID 39779613, 2025). "mTOR activation is thought to be critical for maintaining NK cell proliferation and cytotoxicity 42, whereas another study has shown that the hypoxic environment in cancer leads to sustained activation of the mTOR-Drp1 pathway, which triggers mitochondrial dysfunction in infiltrating NK cells." (PMID 40959272, 2025). "Moreover, nanoparticles should demonstrate high drug loading and encapsulation efficiency for the suppression of PI3K/AKT/mTOR axis in cancer therapy." (PMID 40740483, 2025). "mTOR is essential for promoting stem cell differentiation, facilitating the growth and proliferation of stem and progenitor cells, and influencing the differentiation pathways of multipotent stem cell populations in cancer cells." (PMID 40287470, 2025). "To explore this hypothesis, we examined the relationship between Ephexin1 expression and mTOR activation across various cancer cell lines." (PMID 40855114, 2025). "Therefore, mTOR inhibitors, such as rapamycin and its derivatives, are actively studied and applied in cancer treatment." (PMID 40673277, 2025). "Over-expression of PI3K/AKT may lead to the over-activation of mTOR, which in turn will end up in the development of cancer cells or other diseases." (PMID 38584538, 2025). "Furthermore, LIQ exerts its antitumor potential by inhibiting several signaling pathways, such as NF-κB, PI3K/Akt/mTOR, MAPK, JNK, and their associated proteins, which play crucial roles in cancer progression." (PMID 40723212, 2025). "Pharmacological mTOR inhibition using rapamycin suppressed these pro-cancer phenotypes, suggesting that targeting protein synthesis may offer a therapeutic avenue for the management of FA− associated cancers." (PMID 40805278, 2025). "Inhibiting autophagy via mTOR suppression in cancer cells enhances therapeutic efficacy." (PMID 40076496, 2025).
cancer (continued). "Therefore, mTOR inhibitors, especially those targeting mTORC1, have been developed to treat cancers." (PMID 40740483, 2025). "What is more, silencing B7-H3 expression has been found to enhance the sensitivity of cancer cells to mTOR inhibitors and paclitaxel by disrupting the JAK2/STAT3 signaling pathway, while B7-H3-induced activation of the Raf/MEK/ERK signaling has been implicated in promoting lung metastasis." (PMID 40801642, 2025). "Multiple mTOR inhibitors have been used in clinical trials for various cancer types." (PMID 41160695, 2025). "Together, the expanding arsenal of mTOR inhibitors, which are capable of targeting different branches of mTOR signaling, either alone or in combination with genotoxic agents or immunotherapies, represents a powerful toolkit for the treatment of cancer and other diseases." (PMID 41469379, 2025). "In addition, mTOR, a factor implicated in GJA1-20k expression in cardiac and cancer cells, was also associated with the trafficking of mitochondria to the cortical cytoskeleton, thereby supporting lamellipodia dynamics in epithelial cancer cells." (PMID 39936974, 2025). "Consequently, natural mTOR signaling system inhibitors can decrease the growth of malignant cells, making this a prominent therapeutic target in the management of cancer." (PMID 40717210, 2025). "An alternative mechanism for the therapeutic properties of SeNPs is autophagic death of cancer cells, which can be triggered by enhancing signaling pathways associated with beclin-1, suppressing the p62 protein and by inhibiting the PI3K/AKT/mTOR pathway." (PMID 38994955, 2024). "Importantly, we identified SF3B3 as a critical regulator of mTOR splicing and autophagy in multiple cancers, including CRC." (PMID 38671459, 2024). "The mTOR pathway is a key player in the metabolic reprogramming of cancer cells." (PMID 38893278, 2024). "Furthermore, the maintenance of pluripotency or differentiation into specific types of cancer cells depends on the regulation of the mTOR signal in CSCs." (PMID 39349424, 2024). "The mTOR signaling pathway plays a well-established role in metabolism regulation or even reprogramming of cancer cells, while the process of PDAC tumor growth and liver metastasis consumes and demands a considerable amount of nutrients, one of which is cholesterol." (PMID 39048994, 2024). "Activated Akt then affects the downstream proteins such as mTOR to promote cancer progression." (PMID 38891847, 2024). "However, mutations in the mTOR gene, as well as loss of function mutations in TSC1, TSC2 (tuberous sclerosis proteins 1 and 2), or STK11 (serine/threonine kinase 11), make cancer cells sensitive to mTOR inhibitors." (PMID 39410536, 2024). "Conversely, factors associated with lower rejection rates include a longer time between transplantation and cancer diagnosis, the use of mTOR inhibitors, the maintenance of at least two immunosuppressive drugs at the time of ICPI initiation, and deceased donor kidney transplantation." (PMID 39654653, 2024). "Thus, potentially, modulation of the activity of NLRP1 and NLRP3, due to the effect of PUFA metabolites (majorly, 4-HNE, 8-isoprostanes, and PGE2) on mTOR signaling, appears as a prominent pharmacotherapeutic target, especially in the case of cancer therapies." (PMID 39290706, 2024). "They reported that DPP-4 inhibitors may promote cancer progression via induction of the CXCL12/CXCR4/mTOR axis, which is also important for vascular damage in cancer tissue." (PMID 39135967, 2024).
cancer (continued). "KEGG analysis highlighted involvement in pathways such as ' signaling pathways regulating pluripotency of stem cells,' pathways in cancer,' ' mTOR signaling pathway,' ' GnRH signaling pathway,' and ' Wnt signaling pathway ', implicating RUNX1's role in tumorigenesis." (PMID 39309442, 2024). "By targeting mTOR, these miRNAs may help overcome radioresistance in cancer cells, leading to improved treatment outcomes and potentially reducing the risk of tumor recurrence." (PMID 38965615, 2024). "Targeting the Akt/mTOR signaling pathway can be a promising strategy for the treatment of cancer." (PMID 38921563, 2024). "PTEN acts as an essential negative regulator of the PI3K/AKT/mTOR signaling pathway to suppress cell growth and survival, whereas loss of PTEN, frequently seen in human cancers, results in hyperactivation of the PI3K/AKT/mTOR pathway to promote growth and survival of cancer cells." (PMID 39871893, 2024). "AKT and mTOR are desired targets for pharmacological intervention in cancer therapy." (PMID 38183094, 2024). "Interestingly, mTOR inhibitors have been shown to suppress EMT and cancer stem cell traits induced by FBXW7 mutations." (PMID 39749199, 2024). "In addition, MP1 shows synergistic anti-cancer efficacies with temsirolimus in MYC-driven MB cells by targeting the mTOR signaling pathway." (PMID 38200580, 2024). "mTOR is a key integrator of growth factor and nutrient signals and a critical mediator of the phosphatidylinositol-3-kinase/protein kinase B/Akt signaling pathway, one of the most frequently dysregulated molecular networks in human cancer." (PMID 38711049, 2024). "Moreover, pentacyclic triterpenoids suppress survival signaling pathways, including PI3K/AKT/mTOR and NF-κB, reducing cancer cell survival and enhancing chemotherapy sensitivity." (PMID 39861671, 2024). "The function of various types of immune components, including T cells, B cells, macrophages, and DCs can be altered via the modulation of mTOR signaling in the tumor microenvironment, suggesting a therapeutic benefit of cancer immunotherapy via targeting the mTOR signaling pathway." (PMID 38791040, 2024). "Consequently, targeting mTOR inactivation has been proposed as a potential therapeutic approach to limiting cancer cell growth in HCC." (PMID 38575697, 2024). "In many cancers, mTOR is activated and controls cell growth and metabolism." (PMID 38438907, 2024). "Following the discovery of its target, the mTOR complex, rapamycin (or sirolimus), and its analogs (everolimus, temsirolimus) became therapeutic options for patients with various types of cancer (e.g., breast, kidney, or central nervous system tumors), but clinical results have been highly variable." (PMID 38339294, 2024). "Highlighting the need for early detection and novel CRC therapies, it examines HBD-1’s ability to inhibit the mTOR pathway, a key regulator of cell growth, positioning defensin-based treatments as a promising approach with evidence for suppressing cancer cell proliferation and tumor growth." (PMID 39123348, 2024). "Consequently, numerous clinical trials have been conducted, involving various types of cancers treated with drugs that inhibit the mTOR pathway." (PMID 39349424, 2024). "During fasting, this process is bolstered by reducing the inhibition of autophagy initiation, primarily through the inhibition of a key regulator called the mammalian target of rapamycin (mTOR) which plays an important role in controlling cell growth and proliferation, particularly in cancer cells." (PMID 39310400, 2024). "Consequently, the phosphoinositide 3-kinase/Akt/mTOR pathway is inactivated, making circIPO7 a potential target for cancer therapy." (PMID 38956466, 2024). "However, the data available in the literature provide insight into the proper interpretation of the role of mTOR signaling in the cancer cell dormancy." (PMID 38418814, 2024).
cancer (continued). "Furthermore, mTOR regulates the expression of survival factors in cancer cells, such as cellular myelocytomatosis (C-MYC), and hypoxia induced gene 1 (HIG1), as well as angiogenic factors, including vascular endothelial growth factor (VEGF)." (PMID 39349424, 2024). "Moreover, these processes are triggered by mTOR signaling and PI3K-Akt-mTOR signaling, which are responsible for driving tumorigenesis and modulating metabolism in cancer cells." (PMID 38233470, 2024). "Elevated MUFA levels, for instance, may activate oncogenic signaling pathways, such as mTOR, promoting cancer cell survival and proliferation." (PMID 39687737, 2024). "The protein expression level of VEGF, E-cadherin, Vimentin, p-PI3k, p-Akt, and p-mTOR in the cancer cells treated by HDAC inhibitor was significantly reduced compared with the drug-resistant group, along with significantly increased expression level of E-cadherin (P<0.05)." (PMID 38645502, 2024). "The identification and understanding of specific miRNAs that target mTOR and their impact on radiosensitivity could pave the way for personalized cancer treatment approaches that optimize the use of RT in individual patients." (PMID 38965615, 2024). "Furthermore, consistent with our findings, there have been reports on the effect of C. procera extracts and cardiac glycosides in the inhibition of the expression of the PI3K/AKT/mTOR pathway in correlation to induce apoptosis cancer cells." (PMID 38527038, 2024). "Indeed, as cancer cells, U937 cells have a high metabolic rate, potentially limiting sensitivity to mTOR inhibition, and certainly differ metabolically from primary monocytes, at least in part, due to continuous proliferation." (PMID 38319716, 2024). "The second complex of mTOR, namely mTORC2, has been demonstrated as playing an important role in the promotion of cancer cell survival, proliferation, growth, and motility based on its ability to enhance the phosphorylation of AktSer473, the key regulator of the insulin/PI3K pathway." (PMID 38334632, 2024). "Among the dysregulation of multiple cell signaling cascades, the constitutive activation of the phosphatidylinositol 3-kinase/Akt (PI3K/Akt) signaling axis and its downstream target molecule, the mechanistic target of rapamycin (mTOR), is commonly observed in many cancers." (PMID 38791040, 2024). "Salinomycin, a potential cancer-fighting medication, triggered cell death by generating reactive oxygen species (ROS), and this process was associated with ROS-driven autophagy by controlling the PI3K/Akt/mTOR and ERK/p38 MAPK signaling pathways." (PMID 38305808, 2024). "Emerging data suggest that mTOR signaling is altered in approximately 30% of cancers." (PMID 39766137, 2024). "The EGFR/PI3K/Akt/mTOR pathway is integral to the progression of various cancers, including NSCLC." (PMID 39682234, 2024). "Moreover, PI3K/AKT/mTOR also controls cancer metabolism and genomic instability, having immunomodulatory potential as well." (PMID 38339127, 2024). "The PI3K/Akt/mTOR pathway inhibition activates autophagy and suppresses cancer cell proliferation." (PMID 38982468, 2024). "A pan-cancer proteogenomic survey of the PI3K/AKT/mTOR pathway conducted on 11,219 tissue samples has shown that nearly one-fifth of tumors have high mTOR pathway activation that cannot be explained by the presence of underlying genomic alterations of the PIK3CA signaling axis." (PMID 39061010, 2024). "Similarly, PIK3CG and mTOR levels increased sharply, suggesting a potential role of miRNA regulation in driving protein expression, which intensifies with cancer aggressiveness." (PMID 39850811, 2024). "Notable effects of doxycycline have been observed in osteosarcoma, where it activates Notch1, a transmembrane receptor and cell differentiation regulator, and inhibits the PI3K/Akt/mTOR signaling pathway, resulting in S-phase arrest, apoptosis, and autophagy of cancer cells." (PMID 39858295, 2024).